RNU7-85P (RNA, U7 small nuclear 85 pseudogene)
Synonyms: U7.85; LOC124902076
Gene: Small nuclear RNA gene on chromosome 8 (79,800,133 to 79,800,195, reverse strand). Ensembl gene ENSG00000238884.
Homologues: Orthologues: macaque U7 (87% identical). Paralogues in human: RNU7-13P (87% identical), RNU7-25P (87% identical), RNU7-41P (86% identical), RNU7-45P (86% identical), RNU7-11P (84% identical), RNU7-2P (84% identical), RNU7-48P (84% identical), RNU7-6P (84% identical), RNU7-8P (84% identical), RNU7-22P (83% identical), RNU7-3P (83% identical), RNU7-57P (83% identical), and 143 more.